HIF1A (hypoxia inducible factor 1 subunit alpha)
Diseases named in the same sentence as HIF1A in open-access papers (continued):
Sharing a sentence is not in itself a finding about the gene and the disease.
methemoglobinemia (1 paper, 2025). An inherited or acquired condition characterized by abnormally increased levels of methemoglobin in the blood. "Nitrite-induced methemoglobinemia reduces oxygen transport, may activate HIF-1α, and diverts energy metabolism toward anaerobic glycolysis, evidenced by hepatic glycogen depletion and lactate accumulation." (PMID 40646769, 2025).
mucormycosis (1 paper, 2024). "We next sought to determine if HIF1α facilitates disease establishment and/or progression in an in vivo murine model of mucormycosis." (PMID 38902255, 2024). "HIF1α signaling is of particular interest to us given its established role in angiogenesis and the angio-invasive nature of mucormycosis." (PMID 38902255, 2024). "We performed indirect immunofluorescence microscopy of lung tissue to examine the protein levels of HIF1α following 4 days of in vivo infection with R. delemar in our mouse model of mucormycosis." (PMID 38902255, 2024). "Invasion of blood vessels in the pathogenesis of mucormycosis leads to tissue hypoxia, which would induce local production of HIF1α." (PMID 38902255, 2024). "In this study, our results show that LW6 inhibited R. delemar activation of HIF1α in HSAEC1-KT airway cells which resulted in inhibition of Mucorales-mediated invasion of the host cells, a process considered critical for the pathogenesis of invasive mucormycosis." (PMID 38902255, 2024). "Importantly, pharmacological inhibition of HIF1α increased survival in a mouse model of pulmonary mucormycosis without reducing fungal burden." (PMID 38902255, 2024).
mucositis (1 paper, 2017). Mucositis is inflammation and damage of the mucous membranes lining the mouth and other parts of the gastrointestinal (GI) tract. "Recently, Hif-1a seems to be a key transcription factor in activating apoptotic cell death in mucositis, and if Hif-1a plays a central role in the development of radiation-induced mucositis, it may also be implicated in the vulnerability of normal oral mucosa that are exposed to radiotherapy." (PMID 29069822, 2017).
myelofibrosis (1 paper, 2021). A partial or complete replacement of the bone marrow stroma by fibrous tissue. "Furthermore, VEGF significantly increased the expression of HIF-1α and eNOS genes, the latter inversely regulated by PI3K and mTOR signaling in the MNC of primary myelofibrosis (PMF)." (PMID 34206393, 2021).
myocardial disease (1 paper, 2024). "In ischemic conditions, HIF-1α promotes cardioprotection, while HIF-2α’s role in myocardial disease is more complex." (PMID 39200130, 2024).
myopic maculopathy (1 paper, 2025). "Among the biomarkers analyzed, HIF-1α and HGF exhibited the strongest correlations with clinical parameters, indicating their potential association with axial elongation and myopic maculopathy, within a complex interplay of hypoxia, inflammation, and structural ocular changes." (PMID 41438149, 2025).
neuroendocrine carcinoma (1 paper, 2014). A malignant neuroendocrine neoplasm composed of cells containing secretory granules that stain positive for NSE and chromogranin. "Some studies have investigated the prognostic factors for SCNEC, looking at molecular markers, such as hypoxia-inducible factor-1α (HIF-1α).HIF-1αhas been studied in neuroendocrine carcinoma (NEC)." (PMID 24980293, 2014).
neuroendocrine prostate tumors (1 paper, 2024). "FoxA2 (neuroendocrine-specific transcription factor) was shown to promote tumorigenesis in cooperation with HIF1α in neuroendocrine prostate tumors." (PMID 39103560, 2024).
neuropathy (1 paper, 2023). A disorder affecting the nervous system that manifests with pain, tingling, numbness, and/or muscle weakness. "The activation of HIF1α also participates in neuropathy-induced nociception." (PMID 36827154, 2023).
nodular goiter (1 paper, 2017). Goiter characterized by discrete tissue mass(es) that may or may not produce thyroid hormones. "Our results showed a higher intensity of bands corresponding to HIF-1α in majority of malignant carcinoma cases in comparison with nodular goiters." (PMID 29084538, 2017).
nodular melanomas (1 paper, 2008). "Among primary nodular melanomas, increased tumor thickness was associated with stronger expression of hypoxia markers TNF-α (p = 0.028) and Apaf-1 (p = 0.05), whereas tumor ulceration was associated with stronger expression of hypoxia markers HIF-1α (p = 0.05) and CAIX (p = 0.03)." (PMID 19061491, 2008).
non-Hodgkin lymphoma (1 paper, 2013). Distinct from Hodgkin lymphoma both morphologically and biologically, non-Hodgkin lymphoma (NHL) is characterized by the absence of Reed-Sternberg cells, can occur at any age, and usually presents as a localized or generalized lymphadenopathy associated with fever and weight loss. "HIF-1α was previously found to be stabilized in non-Hodgkin’s lymphoma cells lines as well as in cells from a significant number of DLBCL patients." (PMID 24312289, 2013).
ocular infection (1 paper, 2013). "The studies described herein examined the role of HIF-1α in disease resolution in BALB/c (resistant, cornea heals) mice after ocular infection with Pseudomonas (P.)aeruginosa." (PMID 23874197, 2013).
oligodendroglial tumor (1 paper, 2008). Oligodendrogliomas are cerebral tumors that are differentiated from other gliomas on the basis of their unique genetic characteristics and better response to chemotherapy. "Overexpression of HIF-1α is shown to be an independent prognostic factor in oligodendroglial tumors and interestingly, it also correlates with the microvessel density in these tumors." (PMID 18173856, 2008).
Opportunistic infection (1 paper, 2022). An infection that is caused by a pathogen that would generally not be able to cause an infection in a host with a normal immune system. "Moreover, the activity of HIF-1α is sensitive to stressful conditions such as hypercapnia, in which the HIF-1α activity is suppressed, and the host is at the risk of opportunistic infections." (PMID 35774228, 2022).
oral cavity tumor (1 paper, 2024). "The oral cavity tumor results reflected data without stratification, namely, we observed a significant decrease in EGLN1 levels compared to normal tissues (p = 0.0032), while EGLN3 and HIF1A mRNA levels were higher (p < 0.0001; p = 0.0012)." (PMID 38928200, 2024).
oral submucous fibrosis (1 paper, 2026). "Moderate and severe HIF1α staining intensity was detected in human samples of oral submucous fibrosis, a precancerous condition." (PMID 41385756, 2026).
Osteopenia (1 paper, 2024). Osteopenia is a term to define bone density that is not normal but also not as low as osteoporosis. "In addition, this study discovered that HIF-1α can effectively prevent osteopenia-related osteopenia by blocking ferritin autophagy." (PMID 39712490, 2024).
ovarian clear cell adenocarcinoma (1 paper, 2013). A malignant glandular epithelial neoplasm characterized by the presence of clear and hobnail cells. "This study reports the involvement of stathmin in the mTOR/HIF-1α/VEGF pathway in ovarian clear cell adenocarcinoma (CCA) during hypoxia." (PMID 23819061, 2013).
Pain (1 paper, 2017). An unpleasant sensory and emotional experience associated with actual or potential tissue damage, or described in terms of such damage. "HIF-1α has also been shown to be involved in the development of peripheral neuropathic pain, demonstrated by HIF-1α gene knockout in primary nociceptive neurons." (PMID 28785202, 2017).
pancolitis (1 paper, 2023). Ulcerative colitis that involves the entire colon. "Analyzing the target parameters determined in the E3 group (pancolitis), we detected that HIF-1α correlated much better with TWI and inflammatory status biomarkers." (PMID 38137357, 2023).
pancreatic disease (1 paper, 2009). "Identification of these modifier genes and further comparative functional analysis utilizing mice deficient in Hif1α and Hif2α will provide insight into the precise molecular mechanisms leading to the development of VHL-associated pancreatic disease." (PMID 19340311, 2009).
papilledema (1 paper, 2018). "The findings of papilledema, RGC injury, and HIF-1α upregulation in this manuscript also suggest that a common vascular component of optic nerve injury during ICP elevation is likely preserved in mice." (PMID 29434244, 2018).
papilloma (1 paper, 2016). A benign epithelial neoplasm that projects above the surrounding epithelial surface and consists of villous or arborescent outgrowths of fibrovascular stroma. "Previous data suggested that tumorigenesis of Tgfbr1/Pten 2cKO mice has evident papilloma stages, and high molecular expression of miR-135b regulates HIF-1α." (PMID 26872381, 2016).
perinatal asphyxia (1 paper, 2020). A disorder caused by a lack of blood flow or gas exchange to or from the fetus in the period immediately before, during, or after the birth process. "The neuroprotective effect of DIM was mediated via inhibition of apoptosis and oxidative stress as well as downregulation of Hif1a mRNA (a hypoxic marker) and miR-181b (an indicator of perinatal asphyxia)." (PMID 32816128, 2020). "DIM also downregulated the mRNA expression of HIF1A-regulated Bnip3 and Hif1a which is a hypoxic marker, and the expression of miR-181b which is an indicator of perinatal asphyxia." (PMID 32816128, 2020).
peripheral nerve injury (1 paper, 2021). Injury to a peripheral nerve. "Peripheral nerve injury activated a characteristic set of signaling pathways in both sexes, including HMGB1 Signaling, TREM1 signaling, IL-6 Signaling, IL-17 Signaling, Integrin signaling, HIF1α Signaling, Oxytocin Signaling, and ILK Signaling." (PMID 34966260, 2021).
peritoneal adhesions (1 paper, 2017). "This unique property could make drugs antagonizing HIF-1α (of which YC-1 is a prototype) outstanding therapeutic tools for the prevention of peritoneal adhesions." (PMID 29030625, 2017).
Peutz-Jeghers syndrome (1 paper, 2021). An autosomal dominant disorder caused by pathogenic variants in the STK11 gene, characterized by hamartomatous polyps in the gastrointestinal tract, mucocutaneous pigmentation and increased risk of GI and extra-GI malignancies. "A mouse model of Peutz-Jeghers syndrome (PJS) with STK11/LKB1 inactivation showed a dramatic HIF-1α increase via the mTOR pathway." (PMID 34831355, 2021).
pheochromocytoma-paraganglioma (1 paper, 2021). A rare neuroendocrine tumor arising from chromaffin cells of the adrenal medulla (pheochromocytoma) or from sympathetic and parasympathetic ganglia (paraganglioma). "In some subjects with inherited pheochromocytoma/paraganglioma (PPG) syndromes, hypoxia-inducible factor 1 alpha (HIF1α) stabilization/activation could lead to an increase in angiotensin converting enzymes (ACE)." (PMID 34684070, 2021).
phyllodes tumor (1 paper, 2005). A benign, borderline, or malignant fibroepithelial neoplasm arising from the breast and rarely the prostate gland. "All this suggests that HIF-1α upregulation in stroma of phyllodes tumors is normoxic and may be caused by changes in the stromal expression of oncogenes, tumor suppressor genes or growth factors." (PMID 16168127, 2005). "Epithelial PDGF expression, which is found in most phyllodes tumors, may cause HIF-1α overexpression." (PMID 16168127, 2005). "Epithelial HIF-1α overexpression in phyllodes tumors was associated with CAIX expression." (PMID 16168127, 2005). "Surprisingly, the normal-appearing epithelium in phyllodes tumors frequently displayed HIF-1α and CAIX expression." (PMID 16168127, 2005). "Stromal HIF-1α overexpression in phyllodes tumors was predictive of disease-free survival (P = 0.032)." (PMID 16168127, 2005). "An abrupt increase in number of microvessels was observed in malignant phyllodes tumors, coinciding with a strong increase in stromal overexpression of HIF-1α from borderline grade to malignant grade." (PMID 16168127, 2005). "Stromal and epithelial overexpression of HIF-1α were found almost exclusively in phyllodes tumors (P = 0.001 and P < 0.001, respectively)." (PMID 16168127, 2005). "In our study, stromal HIF-1α overexpression was related to the grade of phyllodes tumors, with a marked increase from borderline to malignant grade." (PMID 16168127, 2005). "In contrast, coexpression of HIF-1α and CAIX in the epithelium in phyllodes tumors points to epithelial hypoxia, most probably caused by relatively distant blood vessels." (PMID 16168127, 2005). "Although HIF-1α most probably contributes to VEGF expression in phyllodes tumors, VEGF expression seems, at least in part, to be independent from HIF-1α." (PMID 16168127, 2005). "Stromal HIF-1α overexpression in phyllodes tumors was strongly correlated with tumor grade (P = 0.001), with all malignant tumors displaying overexpression." (PMID 16168127, 2005). "Finally, the prognostic value of HIF-1α, its downstream effectors and microvessel counts was also assessed for phyllodes tumors." (PMID 16168127, 2005). "Our results show that HIF-1α is related to diminished disease-free survival and may play an important role in stromal progression of phyllodes tumors." (PMID 16168127, 2005). "Interestingly, concerted CAIX and HIF-1α expression was frequently found in morphologically normal epithelium of phyllodes tumors." (PMID 16168127, 2005). "Another candidate for hypoxia-independent upregulation of HIF-1α in phyllodes tumors is PDGF." (PMID 16168127, 2005). "Surprisingly, we regularly found concerted HIF-1α and CAIX expression in normal appearing epithelium of phyllodes tumors." (PMID 16168127, 2005). "It seems therefore that HIF-1α and CAIX expression in the epithelium of phyllodes tumors merely reflects a physiological adaptation to microenvironmental disturbance by rapidly proliferating stroma with lagging peri-epithelial angiogenesis." (PMID 16168127, 2005). "In phyllodes tumors, the relation between VEGF expression and HIF-1α reached borderline significance." (PMID 16168127, 2005).
phyllodes tumor (continued). "Furthermore, experiments covering a variety of molecular elements such as DNA microarray techniques may unravel the complex mechanisms underlying the presumed nonhypoxic upregulation of HIF-1α in the stromal component of phyllodes tumors and its subsequent influence on tumor progression." (PMID 16168127, 2005). "HIF-1α expression in both compartments of phyllodes tumors was not significantly related to tumor size, both with size cut-off at the median and when used as a continuous variable (data not shown)." (PMID 16168127, 2005). "Necrosis could be detected in only one malignant phyllodes tumor, with no typical peri-necrotic HIF-1α overexpression pattern." (PMID 16168127, 2005). "Because of the focal staining patterns resulting in methodological problems and low numbers, phyllodes tumors with HIF-1α-negative and HIF-1α-positive epithelium were not separately analyzed here." (PMID 16168127, 2005).
pilocytic astrocytoma (1 paper, 2010). Pilocytic astrocytoma is a rare subtype of low-grade glioma of the central nervous system characterized by a well circumscribed, often cystic, brain tumor with a discrete mural nodule and long, hair-like projections that extend from the neoplastic astrocytes. "HIF‐1α was present only in 3 (9%) out of the 32 evaluated pilocytic astrocytomas, and its expression was faint (+) in all these cases." (PMID 20030644, 2010). "Two pilocytic astrocytomas contained necrotic areas, and HIF‐1α was present in the perinecrotic tumor cells in both cases at a faint or moderate intensity." (PMID 20030644, 2010). "Pilocytic astrocytomas do not usually show overt tissue necrosis, and the majority of the tumors did not express HIF‐1α suggesting that tumor endothelial cell KIT expression may not have been HIF‐1α and hypoxia‐mediated." (PMID 20030644, 2010).
pityriasis rosea (1 paper, 2025). A mild, self-limited skin disorder that is most commonly seen in children and young adults. "Additional immune-related phenomena include hepatic cytolysis linked to anti-hypoxia-inducible factor 1-alpha (HIF-1α) autoantibodies, and reactivation of latent human herpesviruses 6 and 7 (HHV-6, HHV-7) leading to pityriasis rosea." (PMID 41301477, 2025).
pneumococcal meningitis (1 paper, 2020). An acute purulent infection of the meninges and subarachnoid space caused by Streptococcus pneumoniae, most prevalent in children and adults over the age of 60. "To investigate the involvement of HIF-1α/VEGF pathway in the course of pneumococcal meningitis, we analyzed mouse and human brain specimen by HIF-1α immunohistochemistry (IHC)." (PMID 32529267, 2020). "Double immunofluorescence staining for HIF-1α with CD31 as an endothelial marker also showed positive nuclei in ECs from three independent cases, indicating HIF-1α activation in brain ECs upon pneumococcal meningitis (online resource)." (PMID 32529267, 2020). "Also, in this in vivo murine pneumococcal meningitis model, we observed an upregulation of HIF-1α and VEGF at the BBB." (PMID 32529267, 2020). "As HIF-1α activation was detectable in pneumococcal meningitis samples, we hypothesized a critical role for this pathway in bacterial transfer across the BBB in infections." (PMID 32529267, 2020). "Furthermore, oxidative stress due to excessive production of reactive oxygen species (ROS) has been reported in several studies during pneumococcal meningitis, again suggesting a potential involvement of HIF-1α, as ROS is a well-known HIF-1α activator." (PMID 32529267, 2020).
polycythemia vera (1 paper, 2021). "However, IL-6 and the JAK1/2 inhibitor Ruxolitinib significantly increased angiogenic factors—endothelial nitric oxide synthase (eNOS), VEGF, and hypoxia-inducible factor-1 alpha (HIF-1α)—in patients with polycythemia vera (PV)." (PMID 34206393, 2021).
primitive neuroectodermal tumor (1 paper, 2021). A malignant neoplasm that originates in the neuroectoderm. "Furthermore, stabilization of HIF1α and up-regulation of MYC have been revealed in central nervous system primitive neuroectodermal tumors (CNS-PNET) animal model." (PMID 33572152, 2021).
pulmonary fungal disease (1 paper, 2014). "Consistent with a potential role for HIF1α in defense against pulmonary fungal disease, A. fumigatus induced a three-fold increase in HIF1α mRNA abundance in the lung compared to PBS inoculated controls." (PMID 25255025, 2014).
radicular cysts (1 paper, 2025). "In radicular cysts, HIF-1α was present both in the cytoplasm and nucleus, with greater positivity noted in the nucleus than in the cytoplasm." (PMID 39657933, 2025). "In radicular cysts, HIF-1α expression was absent in 1 (4.2%), weak in 5 (20.8%), mild in 7 (29.2%), and strong in 11 (45.8%) cases." (PMID 39657933, 2025).
rectum carcinoma (1 paper, 2015). "Over-expression of HIF-1α has been reported in many types of malignancies, including lung, prostate, breast, colon and rectum carcinoma, and in both regional and distant metastases, implying that HIF-1α may play a vital role in tumor progression." (PMID 25993275, 2015).